PVT1 (Pvt1 oncogene)
Diseases named in the same sentence as PVT1 in open-access papers (continued):
Sharing a sentence is not in itself a finding about the gene and the disease.
leukemia (continued). "Taken together, these data strongly suggest that the CDK7 inhibitor can block RNAPII loading at the BETi resistance-specific PVT1 enhancer to suppress MYC transcription, thereby exerting a synergistic anticancer effect toward BETi-resistant leukemia." (PMID 32029739, 2020). "Enforced expression Myc rescued the effects of Pvt1, as well as Lilam and Pilna, knockdown in MLL-AF9 leukemia cells." (PMID 28875933, 2017). "We observe a similar effect in our leukemia model, with MYC protein levels being disproportionately reduced when PVT1 is depleted." (PMID 28875933, 2017). "No significant changes in cell growth were detected before and after ASO treatment, suggesting that the enhancer function of PVT1, but not the transcription of PVT1, is critical for regulating the growth of BETi-resistant leukemia cells." (PMID 32029739, 2020). "A combined BETi and CDK7 inhibitor treatment abolished MYC transcription by impeding RNAPII loading without affecting PVT1-mediated chromatin looping at the MYC locus in BETi-resistant leukemia cells." (PMID 32029739, 2020). "Capitalizing on the CRISPR interference technology, we identified the second intron of IncRNA, PVT1, as a unique bona fide gained enhancer that restored MYC transcription independent of BRD4 recruitment in leukemia." (PMID 32029739, 2020).
esophageal cancer (11 papers, 2017 to 2025). A primary or metastatic malignant neoplasm involving the esophagus. "In esophageal cancer, highly expressed PVT1 significantly promoted invasion of TE-1 and Eca-109 cells by accelerating the epithelial-to-mesenchymal transition (EMT) process." (PMID 33817293, 2021). "Digestive system tumors such as in esophageal cancer, PVT1 upregulation decreased E-cadherinexpression and increased N-cadherin and vimentin expression, and induced epithelial-to-mesenchymal transition (EMT) process." (PMID 30083911, 2019). "Further somatic copy number variation analyses revealed that lncRNAs genome loci copy number amplifications or deletions are involved in part of lncRNAs dysregulation in esophageal cancer tissues, such as PVT1, LINC00887, LINC00964, LINC01415, and WEE2‐AS1." (PMID 29926523, 2018). "The results revealed that many lncRNAs dysregulation are accompanied with CNV, such as PVT1, LINC00887 and LINC00964 with frequency gain, LINC01415 and WEE2‐AS1 with frequency loss in esophageal cancer." (PMID 29926523, 2018). "Knockdown of lncRNA PVT1 reduces cell migration and invasion and increases cell apoptosis via miR-145-mediated inhibition of FSCN1 in esophageal carcinoma cell." (PMID 33614632, 2020).
pulpitis (10 papers, 2019 to 2024). Inflammation of the dental pulp. "ROC curve analysis showed that both PVT1 and miR-128-3p exhibited clinical diagnostic value for pulpitis." (PMID 35723715, 2022). "ROC curves were constructed to assess the diagnostic significance of PVT1 and miR-128-3p for pulpitis." (PMID 35723715, 2022). "It was suggested that PVT1 identified in the saliva of pulpitis patients could have diagnostic value." (PMID 39769365, 2024). "Some researchers also revealed that the knockdown of plasmacytoma variant translocation 1 (PVT1) might suppress the damage in pulpitis cell models induced by lipopolysaccharide (LPS)." (PMID 37238161, 2023). "An ROC curve was drawn to estimate the diagnostic significance of PVT1 and miR-128-3p for pulpitis." (PMID 35723715, 2022). "The expression of the lncRNA PVT1 is increased in samples of human pulpitis as compared with control samples." (PMID 39769365, 2024). "In accordance, augmented levels of PVT1 expression have been reported in the saliva of patients with pulpitis." (PMID 39769365, 2024). "For example, an in‐vitro study revealed an upregulation of PVT1 in the pulpitis cell model, which faciliates injury to human dental pulp cells caused by LPS." (PMID 39254474, 2024). "In the instance of pulpitis, the upregulation of PVT1 promotes inflammation and cytokine and chemokine production, while diminishing the expression of miR-455-5p and indirectly raising the expression of SOCS3 and PLXNC1 and the cytokine cascade." (PMID 36890871, 2023). "In contrast to miR-455-5p, PVT1 was upregulated in pulpitis samples, suggesting a link with pulpitis." (PMID 36890871, 2023). "built a ceRNA network based on differentially expressed data of pulpitis, containing lncRNA PVT1, hsa-miR-455-5p, and 2 mRNAs (SOCS3 and PLXNC1)." (PMID 37275855, 2023). "The PVT1 level was augmented in pulpitis patients compared with healthy controls (p < 0.001), while the level of miR-128-3p showed the opposite trend, that is, the level of miR-128-3p in pulpitis patients diminished statistically significantly (p < 0.001)." (PMID 35723715, 2022). "An in-vitro pulpitis cell model was constructed to evaluate the effects of PVT1 or miR-128-3p on cell proliferation, apoptosis, and inflammatory response." (PMID 35723715, 2022). "This study explored the expression and clinical significance of PVT1 in pulpitis patients, and further investigated the possible regulatory mechanism of PVT1 on pulpitis through in-vitro experiments." (PMID 35723715, 2022). "The expression of PVT1 increased, while the miR-128-3p level decreased, in the saliva of pulpitis patients." (PMID 35723715, 2022). "In future studies, the function of PVT1 and miR-128-3p in pulpitis needs to be further explored, and the sample size of the subject population must be increased to support the experimental results." (PMID 35723715, 2022). "In the present study, PVT1 was found to be elevated in saliva of pulpitis patients, and the PVT1 knockdown restrained the production of inflammatory factors." (PMID 35723715, 2022). "In this study, our qRT-PCR results indicated that PVT1 was upregulated in pulpitis tissue compared with matched normal pulp tissue, suggesting that PVT1 is an important factor contributing to pulpitis." (PMID 31304055, 2019). "Additionally, it was reported that the expression of PVT1 is increased in a model of pulpitis in vitro using LPS-treated human dental pulp cells (LPS-hDPCs)." (PMID 39769365, 2024). "Our results suggested that PVT1 and miR-128-3p may be new targets for pulpitis control or treatment." (PMID 35723715, 2022). "It was showed that PVT1 levels could be used to distinguish pulpitis patients from healthy controls." (PMID 35723715, 2022). "This in-vitro study revealed that the expression of PVT1 was increased in the pulpitis cell model." (PMID 35723715, 2022). "This study revealed that knockdown of PVT1 may suppress the damage in pulpitis cell models induced by LPS via targeting miR-128-3p." (PMID 35723715, 2022).
pulpitis (continued). "ROC curves showed that both PVT1 and miR-128-3p had the potential to diagnose pulpitis." (PMID 35723715, 2022). "In summary, this study preliminarily revealed that PVT1 plays a part in promoting the progression of pulpitis by inhibiting the proliferation of hDPCs and promoting the apoptosis and inflammatory response of hDPCs at the cellular level through targeting miR-128-3p." (PMID 35723715, 2022). "We evaluated the expression of PVT1 by qRT-PCR in pulpitis tissues compared to normal pulp tissues." (PMID 31304055, 2019). "Moreover, the analysis of the modulation of inflammation and apoptosis by PVT1 in animal models of pulpitis could determine the potential of PVT1 as a therapeutic target." (PMID 39769365, 2024). "Additionally, our study further investigated the relationship between PVT1 and miR-128-3p, and we speculated that PVT1 was involved in the development of pulpitis by targeted regulating miR-128-3p." (PMID 35723715, 2022).
rheumatoid arthritis (10 papers, 2019 to 2025). A chronic, systemic autoimmune disorder characterized by inflammation in the synovial membranes and articular surfaces. "PVT1 has also been implicated in dysregulated cells in rheumatoid arthritis patients, including FLSs (fibroblast-like synoviocytes)." (PMID 39062113, 2024). "Previously, the lncRNA plasmacytoma variant translocation 1 (PVT1) was reported to regulate NF-kB signaling by targeting miR-145-5p in rheumatoid arthritis (RA)." (PMID 39317938, 2024). "Aberrant expression of lncRNAs, including FAS-AS1 and PVT1, has been observed in autoimmune diseases such as rheumatoid arthritis, multiple sclerosis, and Sjögren’s syndrome." (PMID 40493320, 2025). "Whereas in rheumatoid arthritis, PVT1 knockdown suppressed IL-1β and IL-6 expression, consistent with our findings of significantly reduced IL-6 expression in the SLE + si-Pvt1 group, while also activating apoptosis in fibroblast-like synoviocytes." (PMID 40493320, 2025). "Downregulation of PVT1 reduces proliferation and IL-1β release while inducing apoptosis of rheumatoid arthritis fibroblast-like synoviocytes (RA-FLS) by mediating the miR-543/SCUBE2 axis." (PMID 39062113, 2024). "More PVT1 and less miR-145-5p were found in fibroblast-like synoviocytes from people with rheumatoid arthritis (RA-FLSs) when TNF-α was present." (PMID 39530095, 2024). "It has been proven that lncRNA PVT1 has the potency to hinder the progression of rheumatoid arthritis (RA)." (PMID 36566205, 2022).
acute lymphoblastic leukemia (9 papers, 2019 to 2024). Leukemia with an acute onset, characterized by the presence of lymphoblasts in the bone marrow and the peripheral blood. "Long non-coding RNA (lncRNA) plasmacytoma variant translocation 1 gene (PVT1) modulates the proliferation and apoptosis of acute lymphoblastic leukemia cells by sponging miR-486-5p." (PMID 36362925, 2022). "Interestingly, Ghetti M. and colleagues demonstrated that acute lymphoblastic leukemia is characterized by the presence not only of PVT1 amplification but also by PVT1 fusion genes (chimeras)." (PMID 35090471, 2022). "Here, we illuminated the role of PVT1 in acute lymphoblastic leukemia (ALL) cell proliferation and apoptosis." (PMID 35152842, 2022). "PVT1 also regulates MYC in acute lymphoblastic leukemia (ALL) where PVT1 can act as an oncogene and drives both the development and progression of this type of blood cancer." (PMID 33134177, 2020). "Concurring with these observations, high levels of circPVT1 (but not total PVT1) were found to be overexpressed in acute lymphoblastic leukemia (ALL) compared to normal bone marrow samples; however, their potential to predict patient outcome remains to be determined." (PMID 31781490, 2019).
acute myeloid leukemia (9 papers, 2015 to 2025). Acute myeloid leukemia (AML) is a group of neoplasms arising from precursor cells committed to the myeloid cell-line differentiation. "One of the lncRNAs that showed upregulation in human acute myeloid leukemia (AML) is lncRNA plasmacytoma variant translocation 1 (PVT1)." (PMID 30046623, 2018). "Afterward, it was discovered that the same amplification of the 8q24 region containing the PVT1 gene leads to the overexpression of circPVT1 and in a lesser amount of the lncRNA PVT1 in acute myeloid leukemia (AML) patients with cytogenetic abnormalities." (PMID 29911069, 2018).
liver fibrosis (9 papers, 2016 to 2024). "Hypoxia, closely linked to liver fibrosis, induces autophagy via the PVT1-miR-152-ATG14 signaling pathway, contributing to HSCs activation under hypoxic conditions in primary mouse HSCs." (PMID 39044218, 2024). "Long non-coding RNAs (lncRNA) plasmacytoma variant translocation 1 (PVT1) has been shown to be associated with liver fibrosis." (PMID 30894138, 2019). "Silencing PVT1 not only inhibited liver fibrosis in vivo but also caused the suppression of activated HSCs in vitro." (PMID 27588491, 2016). "As expected, silencing lncRNA-H19, -MALAT1, and -PVT1, positively correlated with liver fibrosis, resulted in a significant decrease in α-SMA expression in JS-1 cells by approximately 46.59%, 41.02%, and 64.30% (P < 0.001), respectively." (PMID 39044218, 2024). "The expression of PVT1 was up-regulated in the liver tissues of activated HSCs in vitro as well as a mouse model of CCl4-induced liver fibrosis." (PMID 33933107, 2021). "A previous study indicated that PVT1 is highly expressed in fibrotic liver tissues, and knockdown of PVT1 can attenuate collagen deposition and liver fibrosis." (PMID 30894138, 2019). "Our results suggest that PVT1 plays a pro-fibrotic role in liver fibrosis and this is a first report." (PMID 27588491, 2016). "To explore the biological role of PVT1 in liver fibrosis, we firstly detected the expression of PVT1 in primary 2-day-old HSCs and primary 10-day-old HSCs." (PMID 27588491, 2016). "While PVT1 has been previously linked to various human cancers, its role in liver fibrosis has not been elucidated." (PMID 38511056, 2024). "The PVT1 knockdown in primary HSCs was also associated with changes in the markers of the EMT process, indicating a possible mechanism by which this lncRNA promotes hepatic fibrosis." (PMID 32326098, 2020). "We also identify PVT1/miR-152/PTCH1 as a new signaling network in liver fibrosis." (PMID 27588491, 2016). "In this study, we aimed to explore the roles of PVT1 in liver fibrosis." (PMID 27588491, 2016). "Our data suggest that PVT1 was increased during liver fibrosis and may play a role in liver fibrosis." (PMID 27588491, 2016). "Moreover, PVT1 expression was analyzed in carbon tetrachloride (CCl4)-induced liver fibrosis in mice." (PMID 27588491, 2016). "Furthermore, small interfering RNA transfection (siRNA) in JS-1 cells in vitro confirmed that lncRNA-H19, -MALAT1, and -PVT1 promoted liver fibrosis, whereas lncRNA-P21 and -GAS5 had the opposite effect on key fibrotic molecules, including α- smooth muscle actin and collagen I expression." (PMID 39044218, 2024). "However, the role of PVT1 in liver fibrosis remains undefined." (PMID 27588491, 2016). "miR-152 level may be negatively correlated with PVT1 expression in liver fibrosis." (PMID 27588491, 2016). "In this study, whether PVT1 can function as a ceRNA for miRNAs in liver fibrosis was explored." (PMID 27588491, 2016). "The results demonstrated that lncRNA-H19, -MALAT1, -PVT1, -P21 and -GAS5 all participated in liver fibrosis formation after schistosome infection." (PMID 39044218, 2024). "This study reveals the dynamic role of lncRNA-H19, -MALAT1, -PVT1, -P21, and -GAS5 in HSCs activation and liver fibrosis in S. japonicum-infected mice, regulated by the ICOSL/ICOS signaling pathway." (PMID 39044218, 2024). "Like GAS5, lncRNA, including lncRNA-p21, PVT1, HOTAIR, and MALAT1, acts as a ceRNA regarding liver fibrosis." (PMID 32413995, 2020). "In conclusion, we demonstrate that PVT1 can epigenetically inhibit PTCH1 via competitively binding miR-152, contributing to activation of Hh pathway and EMT process in liver fibrosis." (PMID 27588491, 2016). "Collectively, we demonstrate that PVT1 epigenetically down-regulates PTCH1 expression via competitively binding miR-152, contributing to EMT process in liver fibrosis." (PMID 27588491, 2016).
liver fibrosis (continued). "Notably, lncRNA-H19, -MALAT1, and -PVT1 are positively correlated with liver fibrosis, while lncRNA-P21 and -GAS5 are potential inhibitors of the liver fibrosis process." (PMID 39044218, 2024). "Thus, the research indicates that PVT1 epigenetically suppresses PTCH1 expression by competitively binding miR-152, subsequently promoting the EMT process in the context of liver fibrosis." (PMID 38511056, 2024). "PVT1 activates the Hedgehog pathway by enhancing the methylation of Patched1 (PTCH1) and down-regulating PTCH1 expression through competitively binding miR-152, which is a driver of EMT and HSC activation in liver fibrosis." (PMID 33933107, 2021). "PVT1 also activates the Hedgehog pathway by enhancing the methylation of Patched1 (PTCH1) and down-regulating PTCH1 expression through competitively binding miR-152, which is a driver of EMT and HSC activation in hepatic fibrosis." (PMID 32326098, 2020).
lung adenocarcinoma (9 papers, 2017 to 2025). A carcinoma that arises from the lung and is characterized by the presence of malignant glandular epithelial cells. "Previous studies have implicated CBX4 in Wnt/β-catenin activation in lung adenocarcinoma (showing a positive correlation with β-catenin levels) and laryngeal cancer (via the circ_PVT1/miR-21-5p/CBX4 axis)." (PMID 41502529, 2025). "The polymorphism rs13254990 in PVT1 gene is associated with the risk of lung adenocarcinoma in a Chinese northeast population." (PMID 31897242, 2020). "The relationship between polymorphism rs13254990 in PVT1 gene and lung adenocarcinoma was significant." (PMID 31897242, 2020). "In lung adenocarcinoma, circ-PVT1 overexpression is involved in chemoresistance through the miR-145-5p/ABCC1 axis." (PMID 36358938, 2022). "PVT1 recruited EZH2 to the large tumor suppressor kinase 2 (LATS2) promoter and repressed LATS2 transcription, and PVT1/EZH2/LATS2 interactions might serve as new target for lung adenocarcinoma diagnosis and therapy." (PMID 29046366, 2017).
prostate tumors (9 papers, 2011 to 2021). "The risk allele (‘T’) is associated with higher expression of PCAT1, PVT1 and c-myc in prostate tumors." (PMID 32680982, 2020). "Similarly, no studies have established the age- and gender-specific associations with PVT1 despite descriptions in breast and prostate tumors." (PMID 31249809, 2019). "In fact, one of the mechanisms of PVT1 function in prostate tumors, as well as in many other tumors, has been to act as a miRNA sponge in the cytoplasm." (PMID 33430890, 2021). "MiR-1206 is part of a lncRNA transcript of the PVT1 gene and, notably, was found to have lower expression in prostate tumor compared to normal tissue in a previous study." (PMID 33374332, 2020). "Apart from c-myc, high levels of PCAT1 and PVT1 have been reported in prostate tumors, suggesting a common mechanism of their transcriptional dysregulation." (PMID 32680982, 2020). "Paired t-test shows a significant difference in the expression profile for PVT1 exon 4B in prostate tumors with Gleason score ≥8 (2.98 ± 0.539, 95% CI [1.90,4.06]) as compared to those with Gleason score ≤7 (1.32 ± 0.340, 95% CI [0.645,2.07]) with P = 0.009." (PMID 32358016, 2020). "In fact, we observed significant correlation between MYC and PVT1 expression, r2 = 0.54 (p = 0.021 in 18 prostate tumours) and r2 = 0.34 (p = 0.0073 in 59 normal prostates)." (PMID 21814516, 2011). "The long non-coding RNA PVT1 within the amplification SCNA identified on 8q24.21 is overexpressed in both AA breast and prostate tumors, and it was found that the overexpression of the MYC oncogene in tumors depends on PVT1 expression." (PMID 32819446, 2020). "Moreover, PVT1, PCAT1, and PCAT10 were significantly overexpressed in prostate tumors relative to tumor-adjacent normal tissues." (PMID 32059012, 2020).
type 2 diabetes (9 papers, 2011 to 2025). "The lncRNA plasmacytoma variant translocation 1 (PVT1), a RNA gene of the lncRNA class, acts as a diagnostic marker for type 2 diabetes and a contributor to tumor development." (PMID 34775377, 2021).